ENSG00000252230
Gene: Small nucleolar RNA gene on chromosome 19 (34,637,696 to 34,637,781, reverse strand). Ensembl gene ENSG00000252230.
Homologues: Paralogues in human: SNORD111 (58% identical), SNORD111B (45% identical).